GAS5 (growth arrest specific 5)
Diseases named in the same sentence as GAS5 in open-access papers (continued):
Sharing a sentence is not in itself a finding about the gene and the disease.
colorectal cancer (continued). "Several studies have shown that GAS5 is downregulated in tumour tissues compared with corresponding normal tissues, such as breast cancer, renal cell carcinoma, prostate cancer, non-small-cell lung cancer and colorectal cancer." (PMID 28099146, 2017). "However, only two studies evaluated associations of the genetic variation of lncRNA GAS5 with cancers (colorectal cancer and hepatocellular carcinoma), which raised the concern of the differential roles of lncRNA GAS5 in the carcinogenesis progress of different cancer types." (PMID 29207621, 2017). "For instance, YTHDF3 serves as an m6A reader to negatively regulate GAS5, thus triggering YAP phosphorylation and degradation and inhibiting the progression of colorectal cancer." (PMID 38229597, 2024). "GAS5 has been reported to interact with and trigger YAP phosphorylation and degradation to inhibit the progression of colorectal cancer, and to be negatively regulated by the mA reader YTHDF3." (PMID 37355516, 2023). "In colorectal cancer (CRC), with the third highest morbidity, GAS5 plays a cruel role for the cancer prognosis." (PMID 36062165, 2022). "Previous studies showed that the stability of lncRNA GAS5 was destroyed by YTHDF3 and consequently promoted progression of colorectal cancer." (PMID 35183226, 2022). "Several studies have indicated that lncRNA GAS5 sponged miR-34a to activate the mTOR/SIRT1 pathway, thereby restraining the progression of colorectal cancer, and upregulated lncRNA GAS5 reduced cisplatin resistance in non-small cell lung cancer." (PMID 35435104, 2022). "For instance, YTHDF3 recognizes and binds to m6A-modified lncRNA GAS5 and promotes its degradation, which elevates YAP expression and promotes colorectal cancer (CRC) progression." (PMID 34646770, 2021). "This ultimately leads to increased expression of HMGA2, which promotes liver metastasis from colorectal cancer; In CRC, lncRNA GAS5 directly binds to YAP and promotes YAP phosphorylation and ubiquitin-mediated degradation." (PMID 35070987, 2021). "Further study investigates the effects of PTEN, lncRNA growth arrest-specific 5 (GAS5), its target genes, and microRNA-222-3p (miR-222-3p) on motility, invasive capacity, and autophagic flux in colorectal cancer cells (CRCs)." (PMID 32708484, 2020). "Growth arrest specific 5 (GAS5) and LINC00538 (Yiya) are promising prognostic biomarkers for liver metastases in patients with early-stage colorectal cancer." (PMID 29784063, 2018). "Meanwhile, a report pointed out that lncRNA GAS5‐YAP‐YTHDF3 could form a feedback loop and participate in the occurrence and development of colorectal cancer." (PMID 36324258, 2022). "YTHDF3 inhibits colorectal cancer progression by negatively modulating the lncRNA GAS5 to generate a GAS5-YAP-YTHDF3 negative feedback loop." (PMID 34721523, 2021). "By negative feedback, m6A-modification of GAS5 accelerates the metastasis of colorectal cancer through the degradation of GAS5 transcripts that bind to the YTHDF3 protein." (PMID 33050646, 2020). "There are no reports on the role of GAS5 in chemoresistance in colorectal cancer; yet, reports suggest that GAS5 is responsible for tumor suppression, inhibition of proliferation, metastasis and invasion." (PMID 33076450, 2020). "GAS5 has a relatively large number of studies in colorectal cancer, but unfortunately the research is not deep enough, and no clear regulation of gene expression axis has been found." (PMID 30606744, 2019). "Notably, the functional link between lncRNA GAS5 and m6A modification in colorectal cancer has already been proven, where the lncRNA GAS5, YAP signaling, and YTHDF3 formed a negative feedback loop that promoted cancer progression." (PMID 35778697, 2022).
colorectal cancer (continued). "In addition, some scholars found that miR-221 and miR-182-5p are highly expressed in colorectal cancer cells and have a significant negative correlation with GAS5." (PMID 30606744, 2019). "In clinical observations, the expression of lncRNA GAS5 showed a negative correlation with the protein levels of YAP and YTHDF3 in the tumors of colorectal cancer patients." (PMID 39830506, 2024). "On the contrary, YTHDF3 reversibly and selectively binds to the m6A modified GAS5 to trigger the decay of GAS5, thus promoting the progress of CRC and forming a negative feedback loop; In colorectal cancer, lncRNA LINRIS (Long Intergene Non-Coding RNA For IGF2BP2 Stability) is highly expressed." (PMID 35070987, 2021). "YTHDF3 was a novel target of YAP, which could facilitate the degradation of m6A modified lncRNA GAS5, thus uncovering a negative functional loop of lncRNA GAS5-YAP-YTHDF3 axis, and identifying a novel mechanism for m6A induced decay of GAS5 on YAP signaling in the progression of colorectal cancer." (PMID 34345203, 2021).
glioma (75 papers, 2015 to 2025). A benign or malignant brain and spinal cord tumor that arises from glial cells (astrocytes, oligodendrocytes, ependymal cells). "The tumour suppression of GAS5 has been associated with gliomas, and the expression level of this lncRNA correlates with the degree of tumour malignancy and patient survival time." (PMID 38790894, 2024). "GAS5 tumour suppression has been associated with gliomas, and the expression level of this lncRNA is correlated with the degree of tumour malignancy and patient survival time." (PMID 38790894, 2024). "In contrast, GAS5 rs145204276 allele deletion in cervical squamous cell carcinoma, urothelial cell carcinoma, and glioma was associated with lower GAS5 expression and increased tumor risk." (PMID 35736636, 2022). "A polymorphism in GAS5, known as rs145204276, had been connected with glioma susceptibility; patients who carried a GAS5 rs145204276 del allele had a higher chance of having glioma." (PMID 33391419, 2021). "On the other hand, the genetic polymorphism of GAS5 can lead to different effects on tumorigenesis; the SNP rs145204276 del/del genotype of GAS5 was associated with higher susceptibility of glioma." (PMID 33925911, 2021). "It has been reported that lncRNA GAS5 suppressed glioma stem cell proliferation and high expression level of lncRNA GAS5 was associated with the 2-year overall survival rate of patients with glioma." (PMID 33029125, 2020). "Similarly, GAS5 polymorphisms have been linked to glioma progression, where GAS5 expression was dysregulated, resulting in impaired tumor suppression." (PMID 40243746, 2025). "However, to fully reveal the subcellular localization of GAS5 in glioma cells and further define the underlying mechanism by which GAS5 interacts directly with proteins, additional evaluations are warranted." (PMID 36106122, 2022). "In previous research, the GAS5 is associated with the progression of glioma." (PMID 33925911, 2021). "GAS5, which affects tumor susceptibility to glioma and overall survival, may be a target for diagnosis and prognosis in glioma." (PMID 33391419, 2021). "Therefore, GAS5 may be a key factor causing drug resistance in glioma, but its downstream pathways need in-depth study." (PMID 33391419, 2021). "Given the significant overexpression of GAS5 in various cancers, we performed growth and proliferation assays on selected cell lines from colon, gastric, glioma, kidney, lung, prostate and thyroid cancers." (PMID 40451925, 2025). "The GAS5/miR-23a axis also acts as a tumor suppressor in non-small cell lung cancer, ovarian cancer, and glioma." (PMID 39941145, 2025). "For instance, GAS5 modulates the malignant phenotype, migration, and invasion of glioma cells via binding and suppressing miR-18-a-5p." (PMID 39941145, 2025). "Both in vivo and in vitro results demonstrated the therapeutic efficacy of GAS5-based gene therapy against glioma." (PMID 40004468, 2025). "GAS5 transcription is higher in lower-grade gliomas compared to higher-grade gliomas, including GBM." (PMID 38790894, 2024). "Their data showed that GAS5 exerted tumor suppressive functions in glioma stem cells via sponging miR-196a-5p, thus leading to decreased tumor migration and invasion." (PMID 39170516, 2024). "On the other hand, GAS5 overexpression was shown to increase the amount of PRC2 in glioma cells, with the direct binding of GAS5 to EZH2 resulting in reduced promoter methylation and the induction of miR-424 expression." (PMID 38139448, 2023). "In human glioma cells, it was observed that Growth Arrest-Specific 5 (GAS5) is a tumor suppressor which downregulates miR-222 and, as a result, upregulates plexin-C1 and inactivates cofilin, resulting in inhibition of tumor progression." (PMID 37627074, 2023). "The authors reported that GAS5 inhibits the expression of various miRNAs in glioma development, including miR-222, miR-10b, miR-18a-5p, miR-196-5P, and miR-34a." (PMID 37444408, 2023).
glioma (continued). "Conversely, lncRNAs such as MEG3 and GAS5 have shown tumor-suppressive effects by inhibiting glioma cell growth and inducing apoptosis in adults." (PMID 37444408, 2023). "Previous studies have shown that overexpression of growth arrest-specific transcript 5 (GAS5) inhibits the malignant phenotype of glioma cells, including proliferation, migration, and invasion, acting as a tumor suppressor of human gliomas." (PMID 36245971, 2022). "To explore the role of GAS5 in glioma, we determined the expression of GAS5 in 72 glioma samples that were divided into high- and low-grades according to pathological classification." (PMID 36106122, 2022). "Overexpression of GAS5 inhibits cell proliferation, migration, and invasion and promotes the apoptosis of glioma cells." (PMID 35359381, 2022). "Recently, two lncRNAs have been identified as modulators of Cofilin-1 expression/function in different types of gliomas–Growth Arrest-Specific 5 (Gas5) and Aldoa repressor specify transcript (ARST)." (PMID 35447891, 2022). "Our study strongly corroborates the potential of GAS5 as a therapeutic target and clinical predictor of glioma." (PMID 36106122, 2022). "This analysis showed that EPB41L4A-AS1 and GAS5 were correlated with low survival time in patients with brain low grade glioma." (PMID 36119500, 2022). "In this study, we identified a remarkable decrease in GAS5 expression in glioma tissues and cells, which was closely related to the viability and migration of GBM cells and GSCs." (PMID 36106122, 2022). "Colony formation assays indicated a significant decline in the rate of colony formation after GAS5 overexpression, and knockdown of GAS5 increased the colony-forming ability of glioma cells, indicating that GAS5 impaired cell self-renewal." (PMID 36106122, 2022). "qRT-PCR analysis showed that GAS5 expression was lower in high-grade glioma tissues than in low-grade glioma tissues." (PMID 36106122, 2022). "We further discovered that GAS5 inhibited the viability of glioma cells through miR-let-7e and miR-125a by protecting SPACA6 from degradation." (PMID 36106122, 2022). "For instance, the GAS5 SNP rs145204276 has been found to be significantly prevalent in those with glioma and oral cancer." (PMID 35456391, 2022). "LncRNA GAS5, as a tumor suppressor, induces the upregulation of Plexin C1 by decreasing miR-222 levels in human glioma cells, thereby inducing cofilin inactivation and promoting cell migration and invasion." (PMID 35246511, 2022). "GAS5 had been found to be downregulated in different stages of glioma, and was at its lowest in advanced glioma patients." (PMID 33391419, 2021). "One of the genes they reported significantly upregulated after treatment in both ERL-resistant and ERL-sensitive glioma cell lines was the lncRNA growth arrest specific 5 (Gas5)." (PMID 33800703, 2021). "One of the better studied mechanisms of lncRNA GAS5 action is negative regulation of the oncogenic miR-222 by acting as an endogenous sponge, which was first proven in glioma." (PMID 35054253, 2021). "GAS5 in glioma cells directly interacts with EZH2 (Enhancer of Zeste 2 Polycomb Repressive Complex 2 Subunit)." (PMID 34202777, 2021). "Previous studies have suggested that GAS5 plays a significant functional role in glioma, affecting proliferation, metastasis, invasion, and apoptosis." (PMID 33391419, 2021). "The C/D box small nucleolar RNA U76 (SNORD76), which was derived from intron 3 of the GAS5 DNA sequence, was expressed at low levels in primary glioma tissues and glioma cells." (PMID 33391419, 2021). "Dysregulation of a long non-coding RNA, GAS5, has been detected in numerous cancers, including glioma." (PMID 33391419, 2021). "Its level and the level of the transcript ofits host gene, lncRNA GAS5, in glioma cells are 2–3 times lower thanthose in a healthy brain." (PMID 34707896, 2021).
glioma (continued). "Evidence for a correlation between GAS5 and chemosensitivity, and for potential roles for GAS5 in the diagnosis and treatment of glioma, is also presented." (PMID 33391419, 2021). "The discovery that GAS5 negatively regulates miR-222 activity was first reported in glioma, and it was later confirmed in gastric cancer and recently in B ALL as well." (PMID 35054253, 2021). "Here we summarize recent studies that report the role of GAS5 in glioma, and describe the known interactions between GAS5 and miRNAs, and other molecular pathways." (PMID 33391419, 2021). "A GAS5 mimic decreased the levels of miR-18a-5p, and a miR-18a-5p mimic reduced GAS5 expression in glioma." (PMID 33391419, 2021). "In a word, lncRNA GAS5 suppressed cisplatin-induced excessive autophagy and thus increased cisplatin sensitivity in an mTOR-independent manner, suggesting that lncRNA GAS5 was a potential and promising target for overcoming glioma chemoresistance." (PMID 33029125, 2020). "GAS5 was also protective in glioma in which there was reduced expression levels of GAS5 in glioma compared with normal brain tissues." (PMID 31956395, 2020). "By overexpressing GAS5, they found that glioma cells were sensitized to cisplatin by restoring cisplatin‐inhibited mammalian target of rapamycin activation." (PMID 33005738, 2020). "Various studies have shown that lncRNA GAS5 also plays a role in the brain, in fact lncRNA GAS5 can effectively inhibit the proliferation, migration and invasion of glioma cells and promote cell apoptosis through targeting GSTM3 expression." (PMID 32624686, 2020). "CRNDE and SBF2-AS1 are overexpressed and promote the malignant biological behaviors of glioma cells, while Gas5 plays a tumor-suppressive role in glioma cells." (PMID 31186064, 2019). "In the GAS5/miR-196a-5p/FOXO1/PID1 (MIIP) pathway of glioma stem cells, FOXO1 promotes GAS5 transcription and forms a positive feedback loop that regulates the biological behavior of glioma stem cells." (PMID 30736838, 2019). "The most abundant TFs were three members of the AP-2 family – TFAP2A, B, and C, with TFAP2A gene expression correlating positively with GAS5 expression in glioma." (PMID 30824562, 2019). "In conclusion, based on molecular and clinical analysis, our study demonstrated that GAS5 is linked tightly to ribosomal biogenesis and translation initiation in LGG tissues and acts as a predictor of survival in patients with early-stage gliomas." (PMID 30853980, 2019). "Long non-coding RNA (lncRNA) derived from the growth arrest-specific 5 (GAS5) gene has been found to participate in progression of glioma." (PMID 30824562, 2019). "In this study, via bioinformatic analysis, we explored the regulatory mechanisms of GAS5 expression in gliomas and compared its prognostic value in LGG and GBM." (PMID 30853980, 2019). "In this study, we focused on the mRNAs coexpressed with GAS5 in gliomas and how GAS5 controlled the survival of glioma patients." (PMID 30853980, 2019). "Kaplan-Meier survival analysis showed high association between GAS5 expression level and OS in both grade II and grade III gliomas." (PMID 30853980, 2019). "One previous study revealed that GAS5 expression decreased as the histologic grade of glioma increased." (PMID 30853980, 2019). "The same author, in a more recent study, added another miRNA to the targets of GAS5; miR-196a-5p, where GAS5 under-expression in human glioma stem cells enhanced tumor progression through inhibiting this miRNA." (PMID 30289954, 2018). "Gas5 exerts tumor-suppressive functions in human glioma cells by directly targeting miR-222 and regulating the expression of its targets BMF and Plexin C116." (PMID 29700282, 2018). "More recently, well described tumor suppressive lncRNA, GAS5, was described to suppress malignancy of glioma stem cells via a miR-196a-5p/FOXO1 feedback loop and proliferation, migration, and invasion of glioma cells by negative regulation of miR-18a-5p." (PMID 30217088, 2018).